GSDMC (gasdermin C)
Diseases named in the same sentence as GSDMC in open-access papers (continued):
Sharing a sentence is not in itself a finding about the gene and the disease.
lumbar spinal stenosis (3 papers, 2020 to 2024). A spinal stenosis that involves the lumbar region of vertebral column. "Two GWAS-identified variants (rs6651255 and rs7833174) near GSDMC were associated with a predisposition to lumbar spinal stenosis." (PMID 33273635, 2020). "Furthermore, the CC genotypes of rs6651255 and rs7833174 were significantly associated with increased plasma expression levels of GSDMC in patients with lumbar spinal stenosis (P < 0.01)." (PMID 33273635, 2020). "In conclusion, two GWAS-identified variants near GSDMC (rs6651255 and rs7833174) may be related with a predisposition to lumbar spinal stenosis." (PMID 33273635, 2020). "Interestingly, lumbar spinal stenosis has been associated with GSDMC expression in the Chinese population, though the specific role of GSDMC-dependent pyroptosis in lumbar spinal stenosis remains unclear." (PMID 39201755, 2024). "The plasma and mRNA expression levels of GSDMC were significantly higher in patients with lumbar spinal stenosis compared with the control group (P < 0.05)." (PMID 33273635, 2020). "In the current study, we observed the plasma levels GSDMC were significantly higher in lumbar spinal stenosis subgroup compared to the control." (PMID 33273635, 2020). "Furthermore, we identified significantly increased plasma GSDMC levels and related gene expressions in patients with lumbar spinal stenosis." (PMID 33273635, 2020). "Thus, indicating that increased plasma GSDMC levels were significantly observed in patients with lumbar spinal stenosis." (PMID 33273635, 2020). "GSDMC protein and mRNA expression levels may have prognostic qualities as biomarkers for the existence, occurrence or development of lumbar spinal stenosis." (PMID 33273635, 2020).
osteoarthritis (3 papers, 2018 to 2022). A noninflammatory degenerative joint disease occurring chiefly in older persons, characterized by degeneration of the articular cartilage, hypertrophy of bone at the margins and changes in the synovial membrane. "GSDMC is associated with differential methylation patterns in osteoarthritis-related cartilage and subchondral bone cartilage." (PMID 35140737, 2021).
ovarian carcinoma (3 papers, 2023 to 2024). A malignant neoplasm originating from the surface ovarian epithelium. "Through miRNA, these lncRNAs are connected with PRGs such as IRF1, NOD1, GSDMC, NLRP1, PLCG1, GSDME and GZMB to construct a pyroptosis related ceRNA regulatory network in ovarian cancer." (PMID 37859811, 2023). "Thus, we discovered many unproven pyroptosis related regulatory axes in ovarian cancer, such as KRT7-AS—has-miR-205—GSDMC, LINC01094—has-miR-330-3p—IRF1, ZNF32-AS2—has-miR-214—GSDME, and MYCNOS—has-miR-150—NLRP1." (PMID 37859811, 2023). "In the gasdermin family, GSDMA (logFC=1.38557, FDR=5.23e-15) and GSDMC (LogFC=2.298323, FDR=2.06e-38) was significantly overexpressed in ovarian cancer, while the expression of GSDMD (logFC=-1.10275, FDR=8.25e-30) and GSDME (logFC=-2.29572, FDR=1.54e- 46) was significantly lower in ovarian cancer." (PMID 37859811, 2023). "At present, studies have shown that GSDMD 7, 33 and GSDME 32, 33 are the key targets that cause pyroptosis in ovarian cancer cells, while GSDMA and GSDMC have not been proven to be involved in the pyroptosis of ovarian cancer cells, which is consistent with our analysis results." (PMID 37859811, 2023). "Therefore, we performed methylation analysis of 51 PYAGs and showed that AIM2, CASP1, CASP8, GSDMC and NLRP6 exhibited hypomethylation in ovarian cancer, which may provide a new theory to explore the methylation of above five genes to improve potential antitumor efficacy of OC." (PMID 36707884, 2023).
pancreatic adenocarcinoma (3 papers, 2022 to 2026). "Furthermore, Yan’s group pointed that GSDMC functioned as an oncogene that promoting the cell proliferation and migration in pancreatic adenocarcinoma." (PMID 37359371, 2023). "Finally, the depletion of GSDMC inhibits the proliferation, invasion, and migration of pancreatic adenocarcinoma cells." (PMID 36199146, 2022).
breast tumor (2 papers, 2025). "Under hypoxic conditions, GSDMC transcription was enhanced in breast tumor cells, and GSDMC in turn converted TNF-α-induced apoptosis to pyroptosis." (PMID 40236694, 2025). "CD109, AHNAK2, and MFGE8 in breast BRCA1-mut cancers, and B3GNT7, CTSV, and GSDMC in BRCA2-mut breast tumors." (PMID 40647506, 2025).
colitis (2 papers, 2023 to 2024). Inflammation of the colon. "We evaluated epithelial differentiation, cell death and immune infiltration under steady state conditions in a new mouse line deficient in Gasdermin C. The role of Gasdermin C was analyzed in acute colitis, infection and colitis-associated cancer." (PMID 39489845, 2024). "We observed increased GSDMC mRNA expression in IBD patients and cleavage of GSDMC was upregulated in experimental colitis mice, suggesting that GSDMC may be involved in IBD, similarly to GSDME and GSDMD." (PMID 37740137, 2023). "Therefore, we investigated the expression of the GSDMC protein in experimental colitis mice induced by DSS." (PMID 37740137, 2023). "The findings indicate that GSDMC could potentially play a role in the development of experimental colitis, and may be a direction for future research." (PMID 37740137, 2023). "Interestingly, we observed an increase in GSDMC mRNA expression in experimental colitis model." (PMID 37740137, 2023).
colon adenocarcinoma (2 papers, 2022 to 2025). "A decreased survival rate in patients with colon adenocarcinoma was associated with higher levels of GSDMC expression from the TCGA dataset." (PMID 40213993, 2025). "Although the transcript levels of GSDMC were similar among subgroups by fractional analysis according to tumor stage, metastasis, subtype, and age, its expression was significantly higher in colon adenocarcinoma than in normal tissues." (PMID 40213993, 2025). "The somatic mutation of eight risk PRGs (CASP4, GPX4, GSDMC, TLR3, NLRP1, PLCG1, IL18, and IRF1) hardly occurred in PAAD samples but were commonly observed in colon adenocarcinoma (COAD) and stomach adenocarcinoma (STAD) ones." (PMID 35000541, 2022).
esophageal squamous cell carcinoma (2 papers, 2021 to 2022). Esophageal squamous cell carcinoma (ESCC) is a type of esophageal carcinoma (EC) that can affect any part of the esophagus, but is usually located in the upper or middle third. "Saekiet al. reported that GSDMC overexpression inhibited the esophageal squamous cell carcinomas cells growing." (PMID 35922531, 2022).
neuroblastoma (2 papers, 2024 to 2026). Neuroblastoma (NB) is the most common solid, extracranial childhood tumor. "Given GSDMC's emerging roles in cancer biology, might it serve as a novel therapeutic target in neuroblastoma or other PNS‐associated malignancies?" (PMID 41574659, 2026). "We measured the mRNA levels of the gasdermin family genes (GSDMA, GSDMB, GSDMC, GSDMD and GSDME) in all five wild-type NB cell lines to understand the genes activated in neuroblastoma." (PMID 38893185, 2024).
pancreatic ductal adenocarcinoma (2 papers, 2024). An infiltrating adenocarcinoma that arises from the epithelial cells of the pancreas. "This study unveils Gasdermin C (GSDMC) as a transcriptional master regulator of stemness and immune evasion in pancreatic ductal adenocarcinoma, acting downstream of EMT‐inducing factors." (PMID 39297408, 2024).
radiculopathy (2 papers, 2021 to 2026). Disease involving a spinal nerve root (see spinal nerve roots) which may result from compression related to intervertebral disk displacement; spinal cord injuries; spinal diseases; and other conditions. "According to a single article on the investigation of GSDMC in the nervous system, a genome‐wide association study (GWAS) suggested that CCDC26/GSDMC rs7833174 in susceptibility to low back pain with radiculopathy." (PMID 41574659, 2026). "The present study did not support the hypothesis that the SNP rs7833174 located between CCDC26 and GSDMC is associated with LBP with radiculopathy 12 months after an acute episode of LBP with radiculopathy." (PMID 35140737, 2021). "Our data did not support the hypothesis that LBP with radiculopathy 12 months after an acute episode of LBP with radiculopathy is associated with the selected SNPs; SOX5 rs34616559, CCDC26/GSDMC rs7833174 and DCC rs4384683." (PMID 35140737, 2021). "Thus, we aimed to examine if LBP with radiculopathy 12 months after an acute episode of radiculopathy is associated with the selected SNPs; SOX5 rs34616559, CCDC26/GSDMC rs7833174 and DCC rs4384683." (PMID 35140737, 2021). "Thus, we examine if LBP with radiculopathy 12 months after an acute episode of LBP with radiculopathy is associated with the selected single nucleotide polymorphisms (SNPs); SOX5 rs34616559, CCDC26/GSDMC rs7833174 and DCC rs4384683." (PMID 35140737, 2021).
triple-negative breast carcinoma (2 papers, 2024 to 2025). An invasive breast carcinoma which is negative for expression of estrogen receptor (ER), progesterone receptor (PR), and human epidermal growth factor receptor 2 (HER2). "A high expression level of GSDMC predicted better response to PARPi treatment in patients with triple-negative breast cancer (TNBC)." (PMID 37883181, 2024). "Our recent study showed that gasdermin C (GSDMC) cleavage by caspase-8 switched apoptosis to pyroptosis in triple-negative breast cancer (TNBC) and other cancer types, indicating that olaparib may trigger pyroptosis in GSDMC-positive TNBC cells." (PMID 37883181, 2024).
cervical cancer (1 paper, 2021). A primary or metastatic malignant neoplasm involving the cervix. "The gene set enrichment analysis method is used to explore the possible mechanism of GSDMC regulating cervical cancer." (PMID 34778452, 2021).
Cognitive impairment (1 paper, 2023). Abnormal cognition is characterized by deficits in thinking, reasoning, or remembering. "The role of GSDMD and GSDME-mediated pyroptosis in cognitive impairment have been elucidated, but the mechanisms of other gasdermin family members such as GSDMA, GSDMB, GSDMC and DFNB59 in cognitive impairment remained unclear." (PMID 37332874, 2023).
colorectal tumor (1 paper, 2025). "Hypoxic and low‐glucose conditions in tumor tissues trigger colorectal tumor cell pyroptosis via sequential activation of the Caspase‐1/Caspase‐6/GSDMC axis." (PMID 40213993, 2025). "To understand the role of GSDMC in regulating CRC development, we first determined the GSDMC protein level by immunohistochemical assay of a human tissue‐array, which included colorectal tumors and paired non‐tumor tissues from 75 patients." (PMID 40213993, 2025). "Among the GSDM family members, GSDMC showed the most remarkable upregulation (≈tenfold change) in human colorectal tumors." (PMID 40213993, 2025). "Further, OGD treatment resulted in the activation of GSDMC in MC38 and CT26 cells, as well as in freshly isolated primary colon tissues and colorectal tumors from mice." (PMID 40213993, 2025). "We found that the transcriptional levels of GSDMA, GSDMC, and PJVK were significantly increased in human colorectal tumors; while, the expression of GSDMB, GSDMD, and GSDME remained unchanged." (PMID 40213993, 2025).
deafness (1 paper, 2022). An inherited or acquired condition characterized by the complete loss of the ability to hear from one or both ears. "Six types of GSDMs paralogous genes, namely GSDMA, GSDMB, GSDMC, GSDMD, and GSDME [also termed deafness, autosomal dominant 53 (DFNA5)], and pejvakin [PJVK; also termed deafness, autosomal recessive 59 9DFNB59)], have been found in humans." (PMID 36003332, 2022).
inflammatory skin disorders (1 paper, 2024). "Other genes, such as IL-21R, GSDMC, CCR7, TLR9, HAS1/3, IL-17A, IL-22, and CXCL10, have been previously identified as genes associated with various inflammatory skin disorders." (PMID 38612783, 2024).
intestinal cancer (1 paper, 2025). "Thus, our data demonstrate that Caspase‐6, but not Caspase‐8, activates GSDMC in intestinal cancer." (PMID 40213993, 2025).
intestinal infection (1 paper, 2024). "GSDMC has been reported to be involved in type 2 immune responses and intestinal infection and inflammation." (PMID 39489845, 2024). "However, our data show that GSDMC is dispensable for immune homeostasis of the gut in steady state and also in models of intestinal infection, inflammation and cancer development, despite being strongly expressed in the intestinal epithelium in vivo." (PMID 39489845, 2024).
intestinal inflammation (1 paper, 2024). "In this study, we comprehensively analyze the role of GSDMC in the gut using newly generated GSDMC knockout mice and mouse models of intestinal inflammation, infection and tumorigenesis." (PMID 39489845, 2024).
intestinal tumors (1 paper, 2025). "Taken together, our data demonstrate that the expression and activation of GSDMC are significantly increased in intestinal tumors." (PMID 40213993, 2025). "Mechanistically, we revealed that GSDMC was activated by Caspase‐6 in intestinal tumors under hypoxia and low‐glucose condition." (PMID 40213993, 2025). "Similarly, there was an increase in the expression and activation of GSDMC in spontaneous intestinal tumors from Apcmin/+ mice compared with normal intestinal tissue." (PMID 40213993, 2025). "In addition, we determined the mRNA expression levels of GSDMC orthologs by qPCR in mouse intestinal tumors." (PMID 40213993, 2025). "To determine whether GSDMC functions in promoting spontaneous intestinal tumor development, we generated Apcmin/+Gsdmc1−/− and Apcmin/+Gsdmc2–4−/− mice." (PMID 40213993, 2025). "We next investigated whether HMGB1 was involved in GSDMC‐mediated intestinal tumor progression." (PMID 40213993, 2025).
kidney carcinomas (1 paper, 2022). Primary or metastatic malignant neoplasm involving the kidney. "Importantly, we found that the expressions of GSDMB, GSDMC, and GSDMD were higher in kidney carcinomas, and specifically kidney renal clear cell carcinoma (KIRC); which adversely impacted the patient outcome." (PMID 36003332, 2022).
lentivirus infection (1 paper, 2023). Virus diseases caused by the Lentivirus genus. "Moreover, caspase 3 activity, cleaved caspase 3 and cleaved caspase 9 levels were all elevated in HOKs after shGSDMC-lentivirus infection, noting that GSDMC knockdown induced cell apoptosis in HOKs." (PMID 37741915, 2023).
mucinous stomach adenocarcinoma (1 paper, 2022). "GSDMC and GSDMD mutations were more likely associated with mucinous stomach adenocarcinoma." (PMID 35164740, 2022).
oral lichen planus (1 paper, 2023). Oral lichen planus is a chronic inflammatory oral condition of unknown aetiology characterized by T-cell-mediated chronic immune response and abnormal epithelial keratinization cycle. "Keratinocytes undergo apoptosis in the chronic inflammatory disorder oral lichen planus (OLP) and an increase of N6-adenosine methylation (m6A) promotes miR-6858 levels, which downregulates the apoptosis regulator Gasdermin C." (PMID 37741915, 2023).
pancreatitis (1 paper, 2024). Inflammation of the pancreas. "Additionally, we performed immunohistochemistry (IHC) to investigate GSDMC expression in various pancreatic tissues using a TMA with normal pancreas, pancreatitis, primary PDAC lesions, metastases, and lymph nodes." (PMID 39297408, 2024).
psoriasis (1 paper, 2022). An autoimmune condition characterized by red, well-delineated plaques with silvery scales that are usually on the extensor surfaces and scalp. "Interestingly, compared with psoriasis skin-derived S.C cells, control skin cells highly expressed pyroptosis-related genes (CASP4, GSDMA, and GSDMC), suggesting that psoriasis skin-derived S.C cells were not sensitive to pyroptosis." (PMID 35962439, 2022).
Sciatica (1 paper, 2018). Pain in the lower back and hip radiating in the distribution of the sciatic nerve. "All variants in CCDC26/GSDMC that were suggestively associated with CBP showed cross-phenotypic associations with lumbar microdiscectomy for sciatica in a recent GWAS of Icelandic adults (lowest p = 5.6×10−12)." (PMID 30261039, 2018).
serous ovarian cancer (1 paper, 2022). "When compared to healthy ovaries, GSDMD and gasdermin C (GSDMC) expression increases in serous ovarian cancer, while GSDME expression decreases." (PMID 36262473, 2022).
thyroid cancer (1 paper, 2021). "We found that high GSDMC expression was associated with poorer survival, which suggested that GSDMC might participate in tumor cell tumorigenesis and progression in thyroid cancer." (PMID 34627252, 2021).